FOXM1 (forkhead box M1)
Diseases named in the same sentence as FOXM1 in open-access papers (continued):
Sharing a sentence is not in itself a finding about the gene and the disease.
ovarian carcinoma (continued). "FOXM1, whose transcriptional network includes DNA repair genes, has been reported to promote ovarian cancer resistance to taxanes (e.g., paclitaxel and docetaxel), platinum-based drugs (e.g., cisplatin and carboplatin), and PARPi (e.g., olaparib and niraparib)." (PMID 34205406, 2021). "Finally, we discuss the clinical utility of FOXM1, including its potential as a cancer biomarker and as a therapeutic target in ovarian cancer." (PMID 34205406, 2021). "FOXM1 was a key executor in DDX23-induced malignant phenotype of ovarian cancer." (PMID 34966670, 2021). "To determine whether DDX23 contribute to overall FOXM1 function, we performed rescue experiments by co-transfecting the ovarian cancer cells with DDX23 siRNA and FOXM1 plasmid, and examined the cell proliferation and migration." (PMID 34966670, 2021). "It is unknown whether FOXM1 can similarly induce genomic instability and DNA hypomethylation in ovarian cancer cell models." (PMID 34205406, 2021). "Elucidating the relative contributions of different kinases to FOXM1 activation in ovarian cancer may provide novel avenues for therapeutic intervention in this disease." (PMID 34205406, 2021). "Furthermore, cisplatin-resistant ovarian cancer tissues and cells were reported to have increased FOXM1 and FOXM1 was an independent indicator of shorter time to progression in platinum-resistant EOC." (PMID 34205406, 2021). "This landmark study identified FOXM1 as a key oncoprotein in ovarian cancer." (PMID 34205406, 2021). "Additional miRNAs established to target FOXM1 in ovarian cancer are miR-134 and miR-216b." (PMID 34205406, 2021). "In ovarian cancer, FOXM1 has been reported to promote cancer cell stemness." (PMID 34205406, 2021). "Publications on FOXM1 in ovarian cancer have subsequently increased since 2011." (PMID 34205406, 2021). "Deubiquitination serves as an additional mechanism to increase FOXM1 expression in ovarian cancer." (PMID 34205406, 2021). "Two observations support that FOXM1 may also be important for metabolic reprogramming in ovarian cancer." (PMID 34205406, 2021). "In ovarian cancer, miR-370 targets FOXM1 mRNA for degradation." (PMID 34205406, 2021). "Thus, we successfully implemented a complex tissue culture model to ovarian cancer and showed potential benefit of combined FOXM1 inhibition." (PMID 33668819, 2021). "First, FOXM1 gene expression is upregulated in ovarian cancer cells by both the metabolic enzyme aspartate N-acetyltransferase, which is overexpressed and associated with worse clinical outcomes in HGSC, and N-acetylaspartate, which is the most abundant onco-metabolite in HGSC tissues." (PMID 34205406, 2021). "Thiostrepton may be combined with chemotherapy targeting breast and ovarian cancers through its ability to inhibit the expression of the cancer stemness regulator FOXM1, which leads to attenuation of stemness and chemosensitivity, respectively." (PMID 33939112, 2021). "As FOXM1 expression is frequently upregulated in ovarian cancer tissue and is suggested to support chemoresistance, we investigated whether an additional benefit can be achieved by combination of the first-line agent carboplatin with thiostrepton." (PMID 33668819, 2021).
ovarian carcinoma (continued). "However, to date, most FOXM1 expression studies in cancer, including ovarian cancer, have only reported overall FOXM1 protein levels rather than phosphorylated FOXM1 (phospho-FOXM1), which stems from a limited number of antibodies available for PTMs." (PMID 34205406, 2021). "Importantly, FOXM1 overexpression is a robust biomarker for poor prognosis in pan-cancer and ovarian cancer." (PMID 34205406, 2021). "Further study on the relationship between FOXM1 and ovarian cancer metabolism is highly encouraged." (PMID 34205406, 2021). "Additional kinases also promote FOXM1 phosphorylation in ovarian cancer." (PMID 34205406, 2021). "The MAPK/ERK and PI3K/AKT pathways promote FOXM1 activation in cancer, including ovarian cancer." (PMID 34205406, 2021). "Moreover, FOXM1 expression was increased in cisplatin-resistant ovarian cancer cells, and combination treatment with RAME and cisplatin sensitized the cisplatin-resistant ovarian cancer cells, which was likely due to FOXM1 inhibition." (PMID 33053721, 2020). "In ovarian cancer, the gene expression level of FOXM1 was higher than normal tissue." (PMID 33053721, 2020). "Moreover, FOXM1 upregulation in cisplatin-resistant ovarian cancer cells was inhibited by RAME treatment." (PMID 33053721, 2020). "Moreover, by suppressing the expression of the FOXM1 and its target genes, the migration and invasion abilities of ovarian cancer cells were suppressed." (PMID 33053721, 2020). "To figure out whether RAME inhibits the mRNA expression of the FOXM1 target genes by regulating FOXM1 expression, we investigated FOXM1 protein levels in ovarian cancer cell lines treated with RAME." (PMID 33053721, 2020). "The identification of downstream regulators of FoxM1 might provide potentially reliable molecular therapeutic target for ovarian cancer." (PMID 29423068, 2018). "Furthermore, it has been shown that FoxM1 promotes reprograming of glucose metabolism in pancreatic and ovarian cancers." (PMID 29765517, 2018). "The molecular mechanisms responsible for FOXM1 overexpression in ovarian cancer are largely unknown." (PMID 29389895, 2018). "We further focused on epithelial ovarian cancer (EOC) given observations that FoxM1 driven cell cycle pathway is perturbed in these very patients from TCGA and our previous observation on an active role of Drp1 in ovarian epithelial cell layer development in Drosophila." (PMID 27509055, 2016). "FOXM1 dysregulation leads to uncontrolled cell growth and epithelial-mesenchymal transition in somatic malignancies including breast, liver, lung, and ovarian carcinomas." (PMID 27167337, 2016). "We identified FOXM1 as a candidate biomarker of chemoresistance and poor outcome in ovarian cancer." (PMID 25537512, 2015). "We asked whether inhibiting FOXM1 activity could be an effective therapeutic strategy in chemoresistant ovarian cancer." (PMID 25537512, 2015). "Recent analysis of 489 high-grade serous ovarian cancers by the Cancer Genome Atlas consortium indicates that FOXM1 overexpression may be a key, early event driving the growth of epithelial ovarian cancers, especially those with serous pathophysiology." (PMID 25537512, 2015). "Collectively, our findings highlight the importance of FOXM1 in chemoresistance and suggest that FOXM1 inhibitors may be useful for treatment of ovarian cancer." (PMID 25537512, 2015). "FOXM1 may be a useful target for overcoming the chemoresistance of ovarian cancer cells because it is upstream of multiple cancer-related signaling pathways and amplifies β-CATENIN signaling." (PMID 25537512, 2015). "Moreover, FOXM1 hyperactivity is a consistent feature of epithelial ovarian cancer and contributes to ovarian cancer metastasis as well as proliferation." (PMID 25537512, 2015).
ovarian carcinoma (continued). "We used primary human EOC tissues, HGSOC cell lines, mouse and human ovarian surface epithelial (OSE) cells, and a murine transgenic ovarian cancer model to investigate genetic determinants of FOXM1 overexpression in EOC, and to begin to define its functional contribution to disease pathology." (PMID 26243836, 2015). "To test this premise, we examined FOXM1 expression in two additional ovarian cancer cell lines." (PMID 25537512, 2015). "We next studied the role of FOXM1 in ovarian cancer progression." (PMID 25411964, 2014). "In accordance with this hypothesis, we found that FOXM1 knockdown seems more efficient than EXO1 silencing in sensitizing ovarian cancer cells to cisplatin treatment." (PMID 24824601, 2014). "Flow cytometric analysis performed in our study suggested FOXM1 knockdown in the chemoresistant ovarian cancer cell line SKOV3-TR could induce cell death." (PMID 25411964, 2014). "Elevated FOXM1 expression has been reported in many tumor types including ovarian cancer." (PMID 24824601, 2014). "Given that FOXM1 was overexpressed in ovarian cancer, and was further up-regulated in response to cisplatin treatment, we hypothesized that targeting FOXM1 could sensitize ovarian cancer cell to cisplatin." (PMID 24824601, 2014). "Our data suggests that EXO1 mediate FOXM1-activated DSB repair in ovarian cancer." (PMID 24824601, 2014). "Novel treatments, such as FOXM1 inhibitor co-treatment with platinum, are potential therapeutic strategies to reduce the necessary dosage of cisplatin and enhance the therapeutic efficacy in treating ovarian cancer." (PMID 24824601, 2014). "In this study, we investigated the expression pattern of FOXM1 in ovarian cancer." (PMID 25411964, 2014). "However, FOXM1 expression remained relatively constant at high levels in SKOV3-TR upon paclitaxel treatment, suggesting a role of FOXM1 in mediating paclitaxel resistance in ovarian cancer cells." (PMID 25411964, 2014). "Moreover, in ovarian cancer, the integrated pathway analysis showed that FOXM1 transcription factor network is significantly altered in 87% of high-grade serous ovarian cancer." (PMID 24824601, 2014). "Ovarian cancers displayed stronger nuclear FOXM1 staining than benign and borderline tumours." (PMID 25411964, 2014). "FOXM1 promotes cell proliferation, migration and invasion in ovarian cancer." (PMID 24824601, 2014). "Previously, it has been shown that FOXM1 is overexpressed in ovarian cancer, and that FOXM1 overexpression was significantly correlated with high-grade ovarian cancers, indicating that FOXM1 may play an oncogenic role in ovarian cancer." (PMID 24824601, 2014). "The result showed there was an increased number of multi-nucleated cells (arrow) in ovarian cancer cells with FOXM1 knockdown (P = 0.03 and 0.01, respectively), suggesting FOXM1 depletion significantly enhanced paclitaxel-mediated mitotic catastrophe in both SKOV-3 and OVCAR3." (PMID 25411964, 2014). "Finally, to determine the extent to which the target (FoxM1) is expressed in ovarian carcinomas, we performed immunohistochemistry on ovarian tumor tissue microarray." (PMID 25426548, 2014). "However, the mechanisms by which FoxM1 is deregulated in ovarian cancer and the extent to which FoxM1 can be targeted in ovarian cancer have not been reported previously." (PMID 25426548, 2014). "We explored whether FOXM1 plays any role in modulating cisplatin sensitivity in ovarian cancer in vitro." (PMID 24824601, 2014). "We further detected the expression of FOXM1 in ovarian cancer cells." (PMID 24885308, 2014). "Oncogenic transcriptional factor FOXM1 has been reported to be overexpressed in ovarian cancer." (PMID 24824601, 2014).
ovarian carcinoma (continued). "Finally, FoxM1 expression is elevated in nearly all (48/49) ovarian tumors, indicating that thiostrepton target gene is highly expressed in ovarian cancer." (PMID 25426548, 2014). "Finally, we demonstrate that EXO1 plays an important role in the DNA repair pathway activated by FOXM1 in ovarian cancer." (PMID 24824601, 2014). "FoxM1 is an oncogenic Forkhead transcription factor that is overexpressed in ovarian cancer." (PMID 25426548, 2014). "Besides, treatment with cisplatin stimulates FOXM1 expression, and gene silencing of FOXM1 sensitizes ovarian cancer cells to cisplatin, through blocking the activation of the DNA repair pathway." (PMID 24824601, 2014). "Since FOXM1 is a key regulator of cisplatin response in ovarian cancer, FOXM1 could be a new therapeutic target in ovarian cancer, and inhibition of FOXM1 would overcome cisplatin resistance." (PMID 24824601, 2014). "Furthermore, knockdown of FOXO3a by transfection with siRNA blocked the casticin-induced down-regulation of FoxM1 expression and inhibited ovarian cancer cell apoptosis." (PMID 23761826, 2013). "We investigated whether casticin was able to regulate FoxM1 expression during casticin-induced apoptosis in ovarian cancer cells." (PMID 23761826, 2013). "A number of studies have demonstrated overexpression of the FoxM1 gene in human cancer cells and tissues, including in ovarian cancer, and emerging evidence suggests that the inactivation of FoxM1 may have important implications in cancer therapy." (PMID 23761826, 2013). "Importantly, we show that these factors are coordinately regulated in GRB7/ERK/FOXM1 signaling axis in ovarian cancer cells." (PMID 23285101, 2012). "But inhibition of ERK signaling by U0126 or PD98059 could reduce the level of FOXM1 in GRB7-overexpressing ovarian cancer cells, suggesting that GRB7, ERK and FOXM1 are regulated orderly." (PMID 23285101, 2012). "Collectively, our findings confer that targeting GRB7/ERK/FOXM1 signaling cascade may be a promising molecular therapeutic choice in combating ovarian cancer." (PMID 23285101, 2012). "Given that the increased GRB7, ERK phosphorylation and FOXM1 significantly correlate with high-grade ovarian tumor, they may be regulated coordinately in order to mediate oncogenic functions in ovarian cancer progression." (PMID 23285101, 2012). "Collectively, our data suggest that over-expression of FOXM1 might stem from the constitutively active ERK which confers the metastatic capabilities to ovarian cancer cells." (PMID 21858223, 2011). "Hence, both U0126 and thiostrepton represent promising starting points to establish anti-cancer therapy in ovarian cancer through the repression of FOXM1." (PMID 21858223, 2011). "Our study indicates that the ERK/FOXM1 signaling cascade may be a promising target for therapeutic intervention in ovarian cancer." (PMID 21858223, 2011). "Taken together, these data confer that FOXM1 isoforms could differentially promote cell proliferation, migration/invasion in ovarian cancer cells." (PMID 21858223, 2011). "Moreover, we provided the first in vitro evidence of ERK/FOXM1 signaling cascade in promoting cell migration/invasion in ovarian cancer cells." (PMID 21858223, 2011). "Collectively, these data suggest that both ERK activity and FOXM1 expression are up-regulated and positively correlated in ovarian cancers, especially in aggressive high-grade tumors, which implicates sharing of a common pathway in ovarian cancer progression." (PMID 21858223, 2011). "FOXM1 overexpression was significantly correlated with high-grade ovarian tumors, indicating that FOXM1 may play an oncogenic role in ovarian cancer, especially in the high-grade subtype." (PMID 21858223, 2011).
ovarian carcinoma (continued). "We hypothesized that thiostrepton can repress the ovarian cancer cell migration/invasion by inhibiting the expression of FOXM1." (PMID 21858223, 2011). "Notably, DE genes by STL001 showed substantial overlap with the FOXM1-KD group in ovarian cancer." (PMID 38697979, 2024). "This prompted us to confirm whether ALKBH5 regulates FOXM1 via PVT1 RNA in ovarian cancer." (PMID 38098223, 2024). "Collectively, our data indicated that HO-ADSCs enhance the migration, invasion, and proliferation of ovarian cancer cells through exosome-mediated FOXM1 mechanisms and that HO-ADSC exosomes could be secreted into ascites and exert a tumor-promoting effect in EOC peritoneal metastasis." (PMID 36359787, 2022). "The results suggest that XST-20 might be a selective inhibitor of FOXM1 in ovarian cancer." (PMID 35680842, 2022). "Moreover, lncPVT1 promoted cisplatin resistance in ovarian cancer by increasing FOXM1 expression." (PMID 35965522, 2022). "Thus, novel GEMMs may provide highly relevant in vivo models to interrogate FOXM1 function in ovarian cancer development and progression." (PMID 34205406, 2021). "In addition, several novel FOXM1 gene targets have been identified in ovarian cancer." (PMID 34205406, 2021). "Overexpression of FOXM1 in high-grade ovarian cancer patients was shown to correlate with resistance against platinum-agents and poor prognosis, with patients quickly building up resistance to standard therapy which was also observed with ovarian cancer cell lines in vitro." (PMID 33668819, 2021). "It is likely that other DUBs may stabilize FOXM1 protein in ovarian cancer." (PMID 34205406, 2021). "Notably, a recent study discovered the expression of additional isoforms of FOXM1 in ovarian cancer, and speculated that these isoforms may be constitutively active." (PMID 26243836, 2015). "Furthermore, KIF2C was identified as a novel FOXM1 transcriptional target that might play a pivotal role in mediating paclitaxel resistance in ovarian cancer cells." (PMID 25411964, 2014). "Thus, FOXM1 might be explored as a candidate of therapeutic target for modulating cisplatin sensitivity in ovarian cancer." (PMID 24824601, 2014). "In the present study, we provide the evidences that FOXM1 and its direct downstream DNA repair gene EXO1 might play in increasing the survival of ovarian cancer cells after cisplatin treatment, and targeting FOXM1/EXO1 axis can sensitize ovarian cancer cell to cisplatin treatment." (PMID 24824601, 2014). "However, it remains elusive whether the FOXM1 play a similar role responsible for conferring cisplatin resistance in ovarian cancer." (PMID 24824601, 2014). "Furthermore, transient FOXM1 depletion is capable of inhibiting ovarian cancer cell migration." (PMID 25411964, 2014). "Thus, we wondered whether inhibition of ERK activity or FOXM1 expression by their specific inhibitors could influence the cell migration and invasion of ovarian cancer cells." (PMID 23285101, 2012). "We also describe the regulatory mechanism of GRB7/ERK/FOXM1 signaling cascade and the inhibition of this signaling using either the chemical inhibitor U0126 or FOXM1 inhibitor Thiostrepton could remarkably abrogate the ovarian cancer cell migration/invasion, and in vitro and in vivo tumor growth." (PMID 23285101, 2012). "However, the functional roles of FOXM1 in ovarian cancer remain largely unexplored." (PMID 21858223, 2011). "However, the expression status and functional roles of FOXM1 in ovarian cancer, especially in cell migration/invasion are largely speculative." (PMID 21858223, 2011). "In ovarian cancer, E2F1-driven DDX23 overexpression modulates FOXM1 splicing, promoting oncogenic FOXM1C isoform generation." (PMID 41303530, 2025).